PLXNB1 (plexin B1)
Description:
Receptor for SEMA4D. Plays a role in GABAergic synapse development (By similarity). Mediates SEMA4A- and SEMA4D-dependent inhibitory synapse development (By similarity). Plays a role in RHOA activation and subsequent changes of the actin cytoskeleton. Plays a role in axon guidance, invasive growth and cell migration.
Synonyms: KIAA0407; PLXN5; SEP; PLEXIN-B1
Tractability: Small molecule: a structure with a bound ligand is known; it has a high-quality binding pocket. Antibody: UniProt places it where antibodies can reach, with high confidence; its Gene Ontology location is reachable by antibodies, with high confidence; UniProt predicts a signal peptide or a membrane-spanning region. PROTAC: ubiquitination databases record sites on it; its protein half-life has been measured.
Gene: Protein-coding gene on chromosome 3 (48,403,849 to 48,430,499, reverse strand). Ensembl gene ENSG00000164050.
Subcellular location: Cell membrane (Isoform 1); Secreted (Isoform 2); Secreted (Isoform 3)
Pathways (Reactome):
Developmental Biology: Sema4D induced cell migration and growth-cone collapse; Sema4D mediated inhibition of cell attachment and migration
Signal Transduction: G alpha (12/13) signalling events; RHOD GTPase cycle
Gene Ontology:
Molecular function: protein binding; semaphorin receptor activity; GTPase activating protein binding; GTPase activator activity; semaphorin receptor binding; transmembrane signaling receptor activity
Biological process: negative regulation of cell adhesion; regulation of cell shape; regulation of cytoskeleton organization; semaphorin-plexin signaling pathway; cell migration; inhibitory synapse assembly; intracellular signal transduction; negative regulation of osteoblast proliferation; neuron projection morphogenesis; ossification involved in bone maturation; positive regulation of axonogenesis; positive regulation of GTPase activity; positive regulation of phosphatidylinositol 3-kinase/protein kinase B signal transduction; positive regulation of Rho protein signal transduction; regulation of cell migration; synapse assembly
Cellular component: extracellular region; plasma membrane; semaphorin receptor complex; glutamatergic synapse; postsynaptic membrane
Genetic constraint (gnomAD): Loss-of-function variants: 106 observed, 202.67 expected, observed/expected ratio (o/e) 0.52, 90% interval 0.45 to 0.62. The upper end of that interval is the gene's LOEUF score, 0.62, which puts it in group 2 of 6, group 1 being the genes least tolerant of losing a copy. Missense variants: 2,323 observed, 2,782.4 expected, observed/expected ratio (o/e) 0.83, 90% interval 0.81 to 0.86. Synonymous variants: 1,151 observed, 1,156.2 expected, observed/expected ratio (o/e) 1, 90% interval 0.95 to 1.04.
Homologues: Orthologues: chimpanzee PLXNB1 (99% identical), macaque PLXNB1 (97% identical), dog PLXNB1 (91% identical), pig PLXNB1 (91% identical), rabbit PLXNB1 (89% identical), guinea pig PLXNB1 (88% identical), mouse Plxnb1 (87% identical), rat Plxnb1 (86% identical), tropical clawed frog plxnb1 (61% identical), zebrafish plxnb1b (57% identical), zebrafish plxnb1a (47% identical), Drosophila melanogaster PlexA (30% identical), and 3 more. Paralogues in human: PLXNB3 (46% identical), PLXNB2 (37% identical), PLXNA1 (32% identical), PLXNA2 (31% identical), PLXNA4 (31% identical), PLXND1 (31% identical), PLXNA3 (31% identical), PLXNC1 (20% identical).
Diseases named in the same sentence as PLXNB1 in open-access papers:
PLXNB1 is named in the same sentence as 83 diseases in open-access papers, as found by Europe PMC text mining. Sharing a sentence is not in itself a finding about the gene and the disease. The quoted sentences say what the papers report.
breast carcinoma (20 papers, 2010 to 2025). "In breast carcinoma cells, when Sema4D binds to Plexin-B1 associated with ErbB2, it induces cell migration and metastasis." (PMID 39769452, 2024). "For instance, a loss of plexin-B1 expression is associated with poor prognosis in ER+ breast cancer patients." (PMID 23050142, 2012). "In human breast cancers, gene expression microarray analysis showed that low Plexin-B1 expression was associated with high histologic grading, ErbB-2 over-expression and a high proliferative index in estrogen receptor-positive breast cancers." (PMID 20858260, 2010). "In breast carcinoma cells, the Sema4D activation of Plexin B1 leads to its tyrosine phosphorylation by MET, creating a docking site for the SH2 domain of Grb2." (PMID 39769452, 2024). "We confirmed that both MCF7 and T47D cells express high levels of Plexin B1, and established that Plexin-B1 serves as the receptor for SEMA3C in ER+ breast cancer cells." (PMID 37443749, 2023). "Plexin-B1–mediated activation of RhoA/C is a key pathway promoting metastasis in ErbB2-mouse models of breast cancer." (PMID 36936664, 2023). "Opposite results were reported in a study that examined the role of plexin-B1 in breast cancer metastasis." (PMID 37627074, 2023). "In that study, knockdown of plexin B1 in MDA-MB-231 cells led to a remarkable increase in the motility of breast cancer cells." (PMID 37627074, 2023). "As noted, all 4 articles of Plexin-B1 group focused on Caucasian breast cancer research, so we only evaluated the relationship between Plexin-B1 level and Caucasian breast cancer patients’ survival." (PMID 30762724, 2019). "The correlation between plexin-B1 expression and estrogen responsiveness in breast cancer cells shows the possible involvement of steroid hormones in plexin-B1 regulation." (PMID 28280798, 2017). "In breast cancer cell lines, plexin B1 was found to be phosphorylated by c-Met, leading to Grb2 (growth factor receptor bound-2) recruitment to the plexin B1/c-Met complex." (PMID 28536399, 2015). "This study demonstrated that the antimigratory or promigratory effects of Sema4D in breast cancer cell lines depend on the stoichiometry of the expression of Plexin-B1, Met and ErbB-2." (PMID 20858260, 2010). "However, the interaction of SEMA4D in disseminating breast cancer cells with PLXNB1 of brain endothelial cells can contribute to the brain-tropic metastasis of cancer." (PMID 40818975, 2025). "Based on our previous report, which suggested that SEMA3C transactivates multiple RTKs through its interaction with Plexin B1, we conducted plexin B1 silencing experiments to investigate whether SEMA3C drives signaling through Plexin B1 in ER+ breast cancer." (PMID 37443749, 2023). "The reciprocal effect of c-Met and ErbB2 in plexin-B1-mediated regulation of RhoA activation status is believed to partially account for the pro- and antimigratory effects of Sema4D in breast carcinoma and other cancer cells, depending on the relative expression levels of these two receptors." (PMID 23050142, 2012). "In addition, overexpression of ErbB2 diminished the binding of c-Met to plexin B1, suggesting that in breast cancer cells and in prostate cancer cells, ErbB2 and c-Met are competing for plexin B1 binding, which largely determines the cellular outcome of Sema4D signalling." (PMID 28536399, 2015). "This is corresponding to their prediction of patient survival outcomes with PLXNB1 showing favorable prognosis, while PLXNB3 and PLXND1 show poor prognosis for both OS and PFI in breast cancer tumors." (PMID 32640719, 2020). "This same pathway was studied in more mechanistic detail in breast carcinoma cells, where SEMA4D signaling via its receptor Plexin-B1 either activated or suppressed cell migration." (PMID 31877778, 2019). "For Caucasian breast cancer patients, SEMA4D's high affinity receptor Plexin-B1 showed a significant positive correlation with survival." (PMID 30762724, 2019).
breast carcinoma (continued). "For instance, a potential role in suppression of malignant melanoma has been described for PLXNB1, while cooperation with ERBB2 and a pro-metastatic role was reported for breast cancer cells." (PMID 27215396, 2016). "Our analysis showed that PLXNA3, B2, and C1 were significantly upregulated, and NRP1, NRP2, PLXNA1, A2, A4 were significantly downregulated, while the rest of the members (PLXNB1, B3 and D1) were not differentially expressed in breast cancer tumors." (PMID 32640719, 2020). "Surprisingly, genes PLXNB1, B3, and D1 showed no significant differential expression in breast cancer tumors compared to normal, but PLXNB1 showed favorable prognosis, and PLXNB3 and PLXND1 showed poor prognosis for both OS and PFI." (PMID 32640719, 2020). "Based on our result, regardless of ErbB-2 or Met took charge, Plexin-B1 was an independent prognosis marker for breast cancer patients." (PMID 30762724, 2019). "Our findings suggest a potential synergy between Plexin-B2 and the RTK Met in glioma cells, which echoes earlier findings on Plexin-B1/Met interaction in promoting tumor growth and invasion of breast cancer and other non-CNS carcinoma cells." (PMID 25762646, 2015). "Upon activation by Sema4D, Plexin-B1 can interact with the receptor tyrosine kinase (RTK) Met to promote migration in several carcinoma cell lines, and similar synergistic interaction of Plexin-B1 with ErbB2 has been reported in breast cancer cells." (PMID 25762646, 2015).
prostate carcinoma (17 papers, 2010 to 2025). A carcinoma that arises from epithelial cells of the prostate gland. "Somatic missense mutations in Plexin-B1 have been detected in patient samples of prostate cancer metastases." (PMID 36936664, 2023). "Thirteen somatic missense mutations in the cytoplasmic domain of Plexin-B1 were found in 46% of prostate cancers." (PMID 29971044, 2018). "For example, using this approach, mutations in plexin-B1 in were identified in 46% of primary prostate cancers but it is difficult to determine the exact percentage of tumor cells in a tumor with that mutation." (PMID 22389719, 2012). "Studies of prostate cancer samples show that mutations present in the Rac binding domain of Plexin-B1 result in an increase in cell motility." (PMID 21966369, 2011). "We found that a series of Plexin-B1 mutations in the hydrophobic interface, Trp1807GluPlex, Leu1815ProPlex (previously linked to prostate cancer), and Leu1815GluPlex, completely abolished its interactions with Rac1* and Rnd1." (PMID 21912513, 2011). "In human prostate cancers, Plexin-B1 and Sema4D are strongly associated and highly expressed compared to the non-neoplastic tissue (77% versus 6% and 58% versus 3.5% respectively)." (PMID 20858260, 2010). "To understand the contribution of the clinically relevant Plexin-B1(P1597L) mutation to prostate cancer progression, we established two lines of mice carrying a targeted insertion of either PLXNB1WT or PLXNB1P1597L cDNA preceded by a flox-STOP-flox cassette into the Rosa26 locus." (PMID 36936664, 2023). "In contrast, impairment in the Plexin-B1 inhibitory pathway due to mutation, together with over-expression of Plexin-B1 would allow its stimulatory signals to prevail and act as an oncogene such as in prostate cancer." (PMID 20858260, 2010). "Mutations in Plexin-B1 are frequently detected in primary and metastatic prostate cancers." (PMID 20858260, 2010). "The TMPRSS2-ERG fusion gene was found to enhance the expression of plexin-B1 in prostate cancer cells." (PMID 37627074, 2023). "The upregulated plexin-B1 was observed to enhance TMPRSS2-ERG induced prostate cancer-derived VCaP cell migration and invasion." (PMID 37627074, 2023). "Together, these results indicate that systemic inhibition of Plexin-B1 has potential as a treatment for prostate cancer." (PMID 36936664, 2023). "Together, our results have demonstrated that Plexin-B1 has a complex yet significant role in metastasis and is a potential therapeutic target to block the lethal spread of prostate cancer." (PMID 36936664, 2023). "Data on the prognostic significance of Plexin-B1 in prostate cancer are complicated by the use of different baseline comparators." (PMID 36936664, 2023). "This pathway has potential as a therapeutic target in locally advanced or oligometastatic prostate cancer, particularly when mutant Plexin-B1 is present." (PMID 36936664, 2023). "Our results demonstrate that Plexin-B1 plays a complex yet significant role in metastasis in mouse models of prostate cancer and is a potential therapeutic target to block the lethal spread of the disease." (PMID 36936664, 2023). "Oncomine analysis revealed that transcript levels of Plexin B1 were elevated in prostate cancer samples compared to normal prostate tissue in three independent microarray gene expression profiling studies." (PMID 29348142, 2018). "Consistent with this, from Oncomine analyses of multiple data sets, Plexin B1 transcript levels were elevated in prostate cancer versus normal prostate tissue samples." (PMID 29348142, 2018). "Sema4D/Plexin-B1 increased the proliferative and invasive potential of LNCaP prostate cancer cells through the activation of ErbB2 and Akt, but decreased the motility and proliferation of PC3 prostate cells." (PMID 29971044, 2018). "We next performed Oncomine analysis to explore the potential clinical relevance of Plexin B1 in prostate cancer." (PMID 29348142, 2018).
prostate carcinoma (continued). "We find that Plexin-B1 plays a significant role in the spread of prostate cancer, with high expression of the clinically relevant P1597L-mutant enhancing metastasis but expression of the WT protein suppressing it, likely through activation of the Rho/ROCK (Rho-associated protein kinase) pathway." (PMID 36936664, 2023). "This hypothesis is consistent with our in vitro findings: knockdown of Plexin-B1 reduces migration and invasion in prostate cancer cells expressing ErbB2, while activation of endogenous Plexin-B1 with Sema4D promotes migration and invasion." (PMID 36936664, 2023). "While no Sema4D mutation has been reported in human cancers, Plexin-B1 mutations and copy number changes are noted commonly in various cancers, including melanomas, pancreas, breast, and prostate cancers." (PMID 29971044, 2018). "A large-scale gene expression comparison between prostate cancer and normal tissue showed Plexin-B1 expression was altered in 30% of patients with prostate cancer (z-score = ±2) and Plexin-B1 expression downregulation was three times more common (22.67%) in prostate cancer than its increase (7.33%)." (PMID 36936664, 2023). "Plexin-B1 activation increases phosphorylation and translocation into the nucleus of the androgen receptor (AR), leading to activation of AR-regulated genes, which could play a role in castration resistance in prostate cancer." (PMID 29971044, 2018). "Taken together, these data suggest that Plexin B1 and coreceptors, NRP1 and NRP2, mediate SEMA3C signaling in prostate cancer cells." (PMID 29348142, 2018).
melanoma (14 papers, 2007 to 2024). A malignant, usually aggressive tumor composed of atypical, neoplastic melanocytes. "Interestingly, constitutive B-Raf/MEK/ERK signaling was found to be associated with a downregulation of plexin-B1 transcript in melanoma." (PMID 23050142, 2012). "Sema4D expressed on many cancer cells, Plexin-B1 also expression in cancer such as ovarian, melanoma, when Sema4D combined with Plexin-B1, it correlates with tumor immune infiltration, angiogenesis, and tumor progression in melanoma." (PMID 37096066, 2023). "Plexin B1, Sema4D receptor, is a tumor-suppressor protein for melanoma, which functions, in part, through inhibition of the oncogenic c-Met tyrosine kinase receptor." (PMID 36777724, 2023). "Introducing Plexin-B1 into melanoma cells suppresses c-Met and hence proliferative responses to HGF." (PMID 29971044, 2018). "In preclinical models, plexin B1 suppressed proliferation, enhanced migration, stimulated Akt activation and, of particular interest, has been reported to render melanoma cell lines resistant to cisplatin-induced apoptosis." (PMID 26052356, 2015). "Restoring plexin-B1 expression in melanoma cells is sufficient to suppress anchorage-independent growth in vitro and inhibit tumor growth in xenograft transplants in nude mice." (PMID 23050142, 2012). "Tumor suppressor function of plexin-B1 has been demonstrated in melanoma cells, and its expression is downregulated by oncogenic B-Raf signaling via MEK/ERK pathway." (PMID 23050142, 2012). "It is plausible that the antitumorigenic functions of plexin-B1 observed in melanoma are adopted in gliomas as well." (PMID 23050142, 2012). "Instead, reconstitution of plexin-B1 expression in melanomas inhibits HGF-dependent activation of c-Met and migration." (PMID 23050142, 2012). "Therefore, we provide the evidence for the first time that Sema4D and Plexin-B1 is related to anti-PD-1 resistance of melanoma." (PMID 37096066, 2023). "Then, we identified 9 LR pairs (“BMP6- > HJV” 、"CCL8- > ACKR4” 、"DLL3- > NOTCH3"、"DSC3- > DSG3"、"GHRH- > GHRHR” 、"LRRC4B- > PTPRF"、"SEMA4D- > PLXNB1"、"SFRP1- > FZD6"、"UCN- > CRHR1′′) as key LR pairs in melanoma prognosis through Lasso Cox regression and Multiple Stepwise Regression." (PMID 36777724, 2023). "Importantly, restoring plexin-B1 expression in melanoma cells is sufficient to suppress tumor growth in vivo, suggesting a tumor suppressor role of plexin-B1." (PMID 23050142, 2012). "Interestingly, a recent study on melanoma also revealed contradicting effects of Plexin-B1 expression on cell migration: enhancement in primary tumor cells but inhibition in metastatic tumor cells." (PMID 20858260, 2010). "Additionally, Plexin-B1 has been reported as a tumor suppressor in melanoma." (PMID 33669221, 2021). "PLXNB1 has previously been shown to be lost in MM and in deeply invasive primary tumors and is strongly inhibited by MAP kinase signaling in melanoma cells and melanocytes." (PMID 26052356, 2015). "Several miR-214 targets have been characterized in various tumor types (ovarian cancer, cervical cancer and melanoma) including MEK3, JNK1, PTEN, Plexin-B1, Ezh2, and TFAP2C and so on." (PMID 22359598, 2012). "Plexin B1 has been shown to inhibit c-Met in response to its ligand hepatocyte growth factor (HGF) and is predicted to be a classic tumor suppressor protein in melanomas in which progression is c-Met dependent." (PMID 26052356, 2015). "Sema4D fails to activate c-Met in melanomas, not because of a significant downregulation of plexin-B1 in these cancer cells." (PMID 23050142, 2012). "A study using Sema4D-expressing melanoma transplants in Plexin-B1 knockout mice, however, showed no significant impairment in tumor angiogenesis." (PMID 20858260, 2010).